PLEKHA6 (pleckstrin homology domain containing A6)
Synonyms: PEPP-3; KIAA0969; PEPP3
Tractability: PROTAC: ubiquitination databases record sites on it; its protein half-life has been measured.
Gene: Protein-coding gene on chromosome 1 (204,218,851 to 204,378,214, reverse strand). Ensembl gene ENSG00000143850.
Subcellular location (Human Protein Atlas): Cell Junctions; Vesicles
Pathways (Reactome):
Metabolism: Synthesis of PIPs at the plasma membrane
Gene Ontology:
Molecular function: protein binding
Genetic constraint (gnomAD): Loss-of-function variants: 53 observed, 96.22 expected, observed/expected ratio (o/e) 0.55, 90% interval 0.44 to 0.69. The upper end of that interval is the gene's LOEUF score, 0.69, which puts it in group 2 of 6, group 1 being the genes least tolerant of losing a copy. Missense variants: 1,226 observed, 1,288.1 expected, observed/expected ratio (o/e) 0.95, 90% interval 0.91 to 1. Synonymous variants: 435 observed, 493.7 expected, observed/expected ratio (o/e) 0.88, 90% interval 0.81 to 0.95.
Homologues: Orthologues: chimpanzee PLEKHA6 (99% identical), macaque PLEKHA6 (98% identical), guinea pig PLEKHA6 (93% identical), dog PLEKHA6 (92% identical), mouse Plekha6 (92% identical), rat Plekha6 (92% identical), rabbit PLEKHA6 (91% identical), pig PLEKHA6 (83% identical), tropical clawed frog plekha6 (63% identical), zebrafish plekha6 (53% identical). Paralogues in human: PLEKHA5 (29% identical), PLEKHA7 (29% identical), PLEKHA4 (17% identical).
Diseases named in the same sentence as PLEKHA6 in open-access papers:
PLEKHA6 is named in the same sentence as 7 diseases in open-access papers, as found by Europe PMC text mining. Sharing a sentence is not in itself a finding about the gene and the disease. The quoted sentences say what the papers report.
breast carcinoma (2 papers, 2022). "But it has been reported that PLEKHA6 was another novel survival predictor, which was associated with breast cancer mortality." (PMID 35073982, 2022). "The molecular function of PLEKHA6 was related to the hormonal receptor, thus leading to the poor prognosis of breast cancer." (PMID 35295857, 2022).
lung carcinoma (1 paper, 2022). "The biological mechanism between PLEKHA6 and lung cancer still remained unclear." (PMID 35073982, 2022). "Also DhMP related gene PLEKHA6 might provide an interesting insight into biological mechanism of lung cancer." (PMID 35073982, 2022). "Using Integrative Genomics Viewer, genome browser plots of the 5hmC locus located in PLEKHA6 and PMEPA1 were illustrated in both lung cancer patients and healthy controls." (PMID 35073982, 2022).
osteoporosis (1 paper, 2024). A condition of reduced bone mass, with decreased cortical thickness and a decrease in the number and size of the trabeculae of cancellous bone (but normal chemical composition), resulting in increased fracture incidence. "Our study systematically identified seven candidate hub genes (PDP1, ALS2CL, VLDLR, PLEKHA6, PPP1CB, MOSPD2, and METTL9) through a combination of various bioinformatics analyses and machine learning algorithms, and provided a nomogram for diagnosing sarcopenia associated with osteoporosis." (PMID 38831425, 2024). "We identified 7 candidate hub genes (PDP1, ALS2CL, VLDLR, PLEKHA6, PPP1CB, MOSPD2, METTL9) and constructed column line plots for osteoporosis combined with sarcopenia." (PMID 38831425, 2024). "A notable finding is the identification of 7 key candidate genes (PDP1, ALS2CL, VLDLR, PLEKHA6, PPP1CB, MOSPD2, and METTL9), and the development of a nomogram for diagnosing osteoporosis in sarcopenia patients." (PMID 38831425, 2024).
cancer (3 papers, 2019 to 2020). A tumor composed of atypical neoplastic, often pleomorphic cells that invade other tissues. "When examining the top 100 gene pairs, BSDC1, C3orf14, CDR2L, LRRC42, MEOX2, NRG2, and PLEKHA6, and SCARF1 were consistently identified by feature selection methods to be associated with cancer status." (PMID 33087122, 2020). "Interestingly, C3orf14, CDR2L, LRRC42, MEOX2, NRG2, and SCARF1 are known carcinogenic genes, while BSDC1 and PLEKHA6 have not been described in previous cancer literature." (PMID 33087122, 2020).
PLEKHA6 also shares sentences with these, for which no sentence is quoted: prostate carcinoma (1 paper); sarcopenia (1); tumor (1).